EGLN2 (egl-9 family hypoxia inducible factor 2)
Description:
Prolyl hydroxylase that mediates hydroxylation of proline residues in target proteins, such as ATF4, IKBKB, CEP192 and HIF1A. Target proteins are preferentially recognized via a LXXLAP motif. Cellular oxygen sensor that catalyzes, under normoxic conditions, the post-translational formation of 4-hydroxyproline in hypoxia-inducible factor (HIF) alpha proteins. Hydroxylates a specific proline found in each of the oxygen-dependent degradation (ODD) domains (N-terminal, NODD, and C-terminal, CODD) of HIF1A. Also hydroxylates HIF2A. Has a preference for the CODD site for both HIF1A and HIF2A. Hydroxylated HIFs are then targeted for proteasomal degradation via the von Hippel-Lindau ubiquitination complex. Under hypoxic conditions, the hydroxylation reaction is attenuated allowing HIFs to escape degradation resulting in their translocation to the nucleus, heterodimerization with HIF1B, and increased expression of hypoxy-inducible genes. EGLN2 is involved in regulating hypoxia tolerance and apoptosis in cardiac and skeletal muscle. Also regulates susceptibility to normoxic oxidative neuronal death. Links oxygen sensing to cell cycle and primary cilia formation by hydroxylating the critical centrosome component CEP192 which promotes its ubiquitination and subsequent proteasomal degradation. Hydroxylates IKBKB, mediating NF-kappa-B activation in hypoxic conditions. Also mediates hydroxylation of ATF4, leading to decreased protein stability of ATF4 (By similarity).
Synonyms: EIT-6; HIF-PH1; HPH-1; PHD1; EIT6; HIFPH1; HPH-3
Tractability: Small molecule: an approved drug acts on it; a structure with a bound ligand is known; a high-quality ligand is known; it belongs to a druggable protein family. PROTAC: UniProt records ubiquitination sites on it; ubiquitination databases record sites on it; a small molecule that binds it is known.
Target class: Enzyme; Oxidoreductase
Gene: Protein-coding gene on chromosome 19 (40,798,996 to 40,808,444, forward strand). Ensembl gene ENSG00000269858.
Subcellular location: Nucleus
Subcellular location (Human Protein Atlas): Nucleoplasm
Pathways (Reactome):
Cellular responses to stimuli: Oxygen-dependent proline hydroxylation of Hypoxia-inducible Factor Alpha
Gene Ontology:
Molecular function: 2-oxoglutarate-dependent dioxygenase activity; ferrous iron binding; hypoxia-inducible factor-proline dioxygenase activity; oxygen sensor activity; peptidyl-proline 4-dioxygenase activity; protein binding; iron ion binding; L-ascorbic acid binding; oxidoreductase activity, acting on paired donors, with incorporation or reduction of molecular oxygen
Biological process: cell redox homeostasis; peptidyl-proline hydroxylation to 4-hydroxy-L-proline; positive regulation of protein catabolic process; regulation of neuron apoptotic process; response to hypoxia; cellular response to hypoxia; estrogen receptor signaling pathway; regulation of cell growth
Cellular component: nucleoplasm; nucleus; cytoplasm
Genetic constraint (gnomAD): Loss-of-function variants: 15 observed, 39.66 expected, observed/expected ratio (o/e) 0.38, 90% interval 0.25 to 0.58. The upper end of that interval is the gene's LOEUF score, 0.58, which puts it in group 2 of 6, group 1 being the genes least tolerant of losing a copy. Missense variants: 492 observed, 588.83 expected, observed/expected ratio (o/e) 0.84, 90% interval 0.77 to 0.9. Synonymous variants: 284 observed, 247.46 expected, observed/expected ratio (o/e) 1.15, 90% interval 1.04 to 1.27.
Homologues: Orthologues: chimpanzee EGLN2 (100% identical), macaque EGLN2 (99% identical), macaque EGLN2 (95% identical), dog EGLN2 (93% identical), rat Egln2 (91% identical), mouse Egln2 (91% identical), guinea pig EGLN2 (90% identical), rabbit EGLN2 (86% identical), tropical clawed frog egln2 (56% identical), zebrafish egln2 (47% identical). Paralogues in human: EGLN1 (43% identical), EGLN3 (33% identical).
Diseases named in the same sentence as EGLN2 in open-access papers:
EGLN2 is named in the same sentence as 87 diseases in open-access papers, as found by Europe PMC text mining. Sharing a sentence is not in itself a finding about the gene and the disease. The quoted sentences say what the papers report.
breast carcinoma (26 papers, 2009 to 2026). "LINC00662 sponges off miR-497-5p from the egl-9 family hypoxia inducible factor 2 (EglN2) and promotes breast cancer cell proliferation, migration, and invasion." (PMID 37583933, 2023). "Research from our group and others has demonstrated that the proline hydroxylase EglN2 is an estrogen-responsive gene that is highly expressed in ER+ breast cancer, including luminal A and B subtypes, and contributes to breast tumorigenesis." (PMID 37207154, 2023). "To further validate our EglN2-subtrate interaction enrichment strategy, we performed a similar experiment in the Triple Negative Breast Cancer (TNBC) cell line MDA-MB-231." (PMID 31729379, 2019). "For example, EGLN2 has been reported to be an unfavourable predictive factor in breast cancer, but functions as a tumour suppressor in colorectal cancer." (PMID 29476053, 2018). "For example, in ER+ breast cancer, EglN2 is mainly regulated by estrogen and acts as a canonical estrogen inducible gene." (PMID 28036276, 2017). "In this paper, by using both xenograft and mouse models, we showed that EglN2 contributes to TNBC breast cancer progression." (PMID 28036276, 2017). "To further examine this, we examined EglN2 protein levels across a panel of established breast cancer cell lines." (PMID 28036276, 2017). "In ER- breast cancer, we report here that EglN2 protein stability is potentially regulated by SCFFBW7 E3 ligase complex." (PMID 28036276, 2017). "Notwithstanding this potential caveat, EglN2 protein upregulation by independent FBW7 hairpins in several different breast cancer cell lines or somatic FBW7 knockout in HCT116 cells validates its negative regulation by FBW7." (PMID 28036276, 2017). "Previous research showed that EglN2 is an ER target gene that plays an important role in ER+ breast cancer." (PMID 28036276, 2017). "Moreover, PHD1 regulation of cyclin D1 has further been demonstrated in breast cancer cells, whereupon inactivation of the Egln2 (Phd1) gene, cyclin D1 levels, and mammary gland cell proliferation decreased." (PMID 34062959, 2021). "In order to examine the effect of FBW7 on EglN2 protein levels in breast cancer cell lines, we downregulated FBW7 expression levels by two independent hairpins in breast cell line MDA-MB-453 with wild type FBW7 expression and found FBW7 depletion led to increased EglN2 and Cyclin E1 levels." (PMID 28036276, 2017). "Since the FBW7 genetic locus is in a region that is frequently deleted in TNBC and the previous research showed that a significant portion of ER- breast cancer cell lines displayed FBW7 loss, hereafter we particularly focus on the effect of FBW7 on EglN2 protein levels in breast cancer cell lines." (PMID 28036276, 2017). "Since FBW7 is an F-box protein that promotes substrate recognition by E3 ligase complex followed by the ubiquitination and degradation, it is reasonable to postulate that EglN2 may act as a potential substrate of the FBW7 E3 ligase complex in breast cancer." (PMID 28036276, 2017). "Depletion of FBW7 in breast cancer cells results in EglN2 protein upregulation." (PMID 28036276, 2017). "Interestingly, a subset of ER- breast cancer cell lines (MCF-12A, MDA-MB-468, BT-549, Hs-578T, HCC1143 and MDA-MB-231) expressed substantial amount of EglN2, albeit slightly lower level than ER+ breast cancer cell lines including T47D, BT474 and ZR-75-1." (PMID 28036276, 2017). "However, the potential post-transcriptional regulation of EglN2 and its physiological role in other subtypes of breast cancer remain largely unknown." (PMID 28036276, 2017). "LncRNA LIPE-AS1 was co-expressed with 5 ferroptosis-related genes (HRAS, PHKG2, MAPK14, EGLN2, and GPX4), including 4 ferroptosis driver and 1 ferroptosis suppressor, and we found that LIPE-AS1 was a protective factor for breast cancer patients’ prognosis." (PMID 34164433, 2021).
breast carcinoma (continued). "In most cases, we observed an increase in EglN2 protein abundance in FBW7 depleted cell lines, suggesting that FBW7 negatively regulated EglN2 protein levels in breast cancer cells." (PMID 28036276, 2017). "In addition, EglN2/PHD1 can act as a transcriptional activator by binding to PGC1α and NRF1 signaling complex in breast cancer." (PMID 33142830, 2020). "Taken together, our results identify EglN2 as a potential therapeutic target in TNBC, and show that FBW7 may regulate EglN2 protein stability in breast cancer." (PMID 28036276, 2017). "To examine whether EglN2 could play a functional role in TNBC, we isolated C3 Tag cell lines from mammary tumors of a transgenic line that mimics human TNBC development." (PMID 28036276, 2017). "Previously, our research indicated that PHD1 (EglN2) promotes the binding of peroxisome proliferator-activated receptor-γ coactivator (PGC1α) with NRF1 under hypoxia and subsequently maintains microchondrial biogenesis in breast cancer through inducing transcription of ferridoxin reductase (FDXR)." (PMID 33808542, 2021).
lung carcinoma (11 papers, 2012 to 2023). "However, subgroup analysis based on cancer type showed that EGLN2 rs10680577 polymorphism was significantly associated with the risk of digestive system cancer under all genetic models, and with the risk of lung cancer under dominant model, heterozygote comparison model, and allele comparison model." (PMID 31414584, 2019). "In lung carcinoma cells, overexpression of EGLN2 induces cell cycle arrest and suppresses proliferation via inhibition of the nuclear factor-κB (NF-κB) activity." (PMID 29476053, 2018). "Notably, EGLN2 and RABAC1 together form part of a 4-gene signature of invasive lung cancer." (PMID 24498427, 2014).
colorectal cancer (9 papers, 2013 to 2024). A primary or metastatic malignant neoplasm that affects the colon or rectum. "In colorectal cancer, the mRNA and protein levels of EGLN2 were lower in the primary cancer than in histopathologically unchanged tissues." (PMID 38928200, 2024). "In addition, PHD1 (EglN2) inhibition and silencing sensitizes colorectal cancer cells to 5-FU chemotherapy." (PMID 33808542, 2021). "In human colon and colorectal cancer, overexpression of EGLN2 could inhibit tumour growth." (PMID 29476053, 2018).
pheochromocytoma (6 papers, 2016 to 2024). "Mutations in some genes have been found only in single patients or families (e.g., MEN1, EGLN1, EGLN2, MDH2, IDH1, BAP1, BRAF); therefore, their role in the formation of paragangliomas/pheochromocytomas cannot be reliably confirmed." (PMID 28187001, 2017).
melanoma (5 papers, 2012 to 2025). A malignant, usually aggressive tumor composed of atypical, neoplastic melanocytes. "The expression levels of CA9 and EGLN2 are significantly upregulated under hypoxic conditions in the malignant melanoma cell line A375." (PMID 40001606, 2025). "In melanoma, its upregulation triggers overexpression of prolyl hydrolase egl-9 family hypoxia inducible factor 2 (EGLN2) through sponging miR-205, a direct target of this transcript." (PMID 34638331, 2021). "EGLN2 is a regulator of endoplasmic reticulum (ER) stress, and although the role of ER stress in cancer is context-dependent, the inhibition of ER stress through NORAD knockdown decreases invasion and migration of melanoma cell lines." (PMID 34638331, 2021).
non-small cell lung carcinoma (5 papers, 2017 to 2024). A group of at least three distinct histological types of lung cancer, including non-small cell squamous cell carcinoma, adenocarcinoma, and large cell carcinoma. "For instance, the prognostic value of HIF1A in non-small cell lung cancer is altered with EGLN2 expression, and gene signature associated with T cell dysfunction can be screened by assessing G × G interactions." (PMID 37553713, 2023). "Similar to our results, in non-small-cell lung cancer, a higher mRNA level of EGLN2 contributes to longer overall survival." (PMID 38928200, 2024). "They found that the expression of EGLN2 was negatively correlated with HIF1A in non-small cell lung cancer." (PMID 37553713, 2023). "Similarly, a decreased mRNA level of EGLN2 was found in non-small-cell lung cancer and was correlated with larger tumors and higher tumor stage." (PMID 38928200, 2024). "For example, in fibrosarcoma and non-small-cell lung cancer cell lines, autophagy-mediated BMAL1 degradation facilitates EGLN2 expression to destabilize HIF1A which ultimately increases lipid peroxidation." (PMID 37845346, 2023).
Autoimmunity (4 papers, 2016 to 2025). The occurrence of an immune reaction against the organism's own cells or tissues. "Novel gene-longevity associations included genes MICA/B (a locus previously linked to autoimmune conditions rheumatoid arthritis and multiple sclerosis), TOX, ZW10, SEMA6D, EGLN2/CYP2A6, EXOC3L2/MARK4 and C20orf187." (PMID 29227965, 2017).
pancreatic cancer (4 papers, 2011 to 2024). "There are other yet unidentified factors, and high-throughput protein–protein interaction screening methods are needed to search for TCF7L2 interacting protein and to further elucidate the underlying mechanisms for EGLN2 silencing in pancreatic cancer." (PMID 29476053, 2018). "The impact of EGLN2 on pancreatic cancer glycolysis was assessed by using the Extracellular Flux Analyzer, and showed that overexpression of EGLN2 inhibited glycolytic capacity." (PMID 29476053, 2018). "Collectively, these observations supported the conclusion that EGLN2 was a negative regulator of proliferation and aerobic glycolysis in pancreatic cancer." (PMID 29476053, 2018). "Collectively, our present study uncovered TCF7L2 and EGLN2 as novel prognostic markers for pancreatic cancer and provided a possible regulatory mechanism." (PMID 29476053, 2018). "As observed, the CCK-8 proliferation assay results demonstrated that overexpression of EGLN2 decreased cell viability maintenance in pancreatic cancer." (PMID 29476053, 2018). "Notably, in pancreatic cancer, decreased expression of EGLN2 and EGLN3 resulted in the induction of angiogenic factors by HIF1A and TGF-β1 pathway and poor patient OS." (PMID 38928200, 2024). "We then examined the influence of EGLN2 on pancreatic cancer viability and proliferation." (PMID 29476053, 2018). "This led us to assume that TCF7L2 might negatively regulate EGLN2 expression in pancreatic cancer." (PMID 29476053, 2018). "On the contrary, the mRNA level of EGLN2 was upregulated in pancreatic cancer compared to matched normal pancreatic regions." (PMID 38928200, 2024). "The research indicated upregulation of TCF7L2 inhibited the promoter activity of Egl-9 family hypoxia-inducible factor 2 (EGLN2) and suppressed its expression, which enhanced the stability of HIF-1α, enhancing glycolysis-related genes expression and increasing glycolysis in pancreatic cancer cells." (PMID 32587480, 2020). "The results demonstrated that among EGLN family members, only decreased expression of EGLN2 resulted in a worse prognosis for pancreatic cancer patients, while the other two family members were not predictive factors for OS." (PMID 29476053, 2018). "However, inconsistent with our in vitro observations, EGLN2 negatively and significantly correlated with HK2 and LDHA expression in pancreatic cancer patients." (PMID 29476053, 2018). "Finally, we analyzed the expressional correlation of EGLN2 with GLUT1, HK2, and LDHA in TCGA pancreatic cancer patients." (PMID 29476053, 2018). "As shown, EGLN2 mRNA and protein levels increased in TCF7L2-silenced pancreatic cancer cells." (PMID 29476053, 2018). "In our present study, we identified TCF7L2 as a novel predictive marker for OS of pancreatic cancer patients, and we provided mechanisms for the metabolism effects, indicating a potential role for TCF7L2 in aerobic glycolysis regulation by targeting the EGLN2/HIF-1α axis." (PMID 29476053, 2018).
polycythemia (4 papers, 2018 to 2024). Abnormally high mass or concentration of red blood cells in the blood, either due to an increase in erythropoiesis or a decrease in plasma volume. "In the patient with the mutation in PHD1 (EGLN2), sensitivity of erythroid progenitors to EPO and erythropoietin receptor (EpoR) activity were inappropriately increased and resulted in polycythemia with no or mild increase in EPO levels with increased EpoR expression." (PMID 30538672, 2018).
glioma (3 papers, 2012 to 2025). A benign or malignant brain and spinal cord tumor that arises from glial cells (astrocytes, oligodendrocytes, ependymal cells). "According to their findings in U87 glioma cells, hydroxylation of P332 by PHD1 (prolyl hydroxylase domain protein 1, encoded by the EGLN2 gene) precedes and is required for successful autophosphorylation of Y273 in DYRK1B." (PMID 41444824, 2025). "Egln2 mRNA was neither highly nor differentially expressed in Rt-glioma or Rt-NSCs, despite the use of several primer sets to probe for this transcript (data not shown)." (PMID 22905089, 2012).
prostate carcinoma (3 papers, 2020 to 2025). A carcinoma that arises from epithelial cells of the prostate gland. "In the context of hypoxia-driven pathways, EGLN2 (egl-9 family hypoxia-inducible factor 2), a key regulator of cellular adaptation to low oxygen, shows elevated expression in prostate cancer, and its ubiquitination by the tumor suppressor SPOP constrains cancer cell growth." (PMID 41468516, 2025).
triple-negative breast carcinoma (2 papers, 2017 to 2019). An invasive breast carcinoma which is negative for expression of estrogen receptor (ER), progesterone receptor (PR), and human epidermal growth factor receptor 2 (HER2). "However, the detailed molecular mechanism(s) underlying the post-transcriptional regulation of EglN2 and its potential role in Triple Negative Breast Cancer (TNBC) remains largely unclear." (PMID 28036276, 2017). "By developing an optimized enzyme-substrate-trapping strategy coupled with TAP-TAG purification and mass spectrometry, here we identify adenylosuccinate lyase (ADSL) as a substrate of the hydroxylase EglN2 in triple negative breast cancer (TNBC)." (PMID 31729379, 2019).
liver cancer (1 paper, 2017). An epithelial or non-epithelial malignant neoplasm that arises from the liver. "The rs10680577 insertion/deletion polymorphism of EGLN2 results in high expression of both EGLN2 and RERT-lncRNA and positively correlates with liver cancer risk." (PMID 29299175, 2017). "It is a potential biomarker for early diagnosis of liver cancer and has been postulated to disrupt the structure of RERT-lncRNA resulting in changes in EGLN2 expression." (PMID 29299175, 2017).
lung adenocarcinoma (1 paper, 2021). A carcinoma that arises from the lung and is characterized by the presence of malignant glandular epithelial cells. "A close relationship between hypoxia (based on HIF-1α expression) and EGLN2 (Egl nine homolog 2) methylation was observed in lung adenocarcinoma and SqCC (n = 1230)." (PMID 34298636, 2021).
migraine (1 paper, 2018). "The under-expression of these genes including the oxygen sensor Egln2 may elevate the level of reactive oxygen species that have been associated with migraine." (PMID 30618656, 2018).
oncocytoma (1 paper, 2008). "Analysis of matched oncocytoma-normal tissue pairs revealed a dramatic increase in the level of EGLN2 in the oncocytoma tumors versus the level observed in corresponding normal tissue." (PMID 18773095, 2008). "Therefore, we propose that the downregulation of BNIP3L is the result of chromosome-pairing induced upregulation of EGLN2 and that downregulation of BNIP3L contributes to the inhibition of apoptosis to facilitate oncocytoma cell survival and growth." (PMID 18773095, 2008).